IL4 (interleukin 4)
Diseases named in the same sentence as IL4 in open-access papers (continued):
Sharing a sentence is not in itself a finding about the gene and the disease.
asthma (continued). "Th2-driven asthma is the most common and is typically characterized by elevated levels of type 2 inflammatory biomarkers, including type 2 cytokines (e.g., IL-4, IL-5, and IL-13), serum IgE, and blood eosinophils." (PMID 35619697, 2022). "In line with plasma IL-4 and IL-25 data, patients with asthma comorbid AR had higher levels of IL-5 (6.94 [5.74, 10.69]) than those without asthma (4.07 pg/ml [3.61, 4.72] pg/ml, P < 0.001)." (PMID 35348596, 2022). "Research on asthma patients and mice models of the disease has shown that activation of Th2 and production of Th2 type cytokines such as IL-13, IL-4, and IL-5, lead to activation of eosinophils and production of IgE." (PMID 36249456, 2022). "Recent studies on atopy and asthma indicate that total IgE levels are positively correlated with the ratio of IL-4/IFN-γ producing cells." (PMID 35513696, 2022). "Most treatments of the type 2 (T2) target phenotype of asthma, in which IL-4, IL-5, and IL-13 modulate the central signals of inflammatory reactions." (PMID 35327702, 2022). "Asthma is characterized by chronic airway inflammation, in which Th2 cells promote the accumulation of eosinophils by secreting interleukin IL-4, IL-5, and IL-13 is the key pathogenesis of asthma." (PMID 35287655, 2022). "Targeting the IL-4/IL-13 axis at various levels of its signaling pathway has emerged as promising targeted therapy in both AR and asthma patient populations." (PMID 35663523, 2022). "These cytokines associated with the Th2 response induce IgE immunoglobulin production by B lymphocytes (IL-4), chemotaxis for eosinophils towards the lung microenvironment (IL-5), mucus and collagen secretion, and bronchial hyperreactivity (IL-13)." (PMID 36685604, 2022). "The association of tissue helminth infections with peripheral blood eosinophilia, the presence of cytokines including IL-10 and IL-4, and elevated IgE levels are hypothetical pieces of evidence for the relationship between HI and asthma." (PMID 36250067, 2022). "Among the various factors related to asthma progression, the Th2 cytokines including IL-13, IL-5, and IL-4 play crucial roles in the advancement of the disease." (PMID 35892624, 2022). "Pediatric asthma is mainly characterized by a T helper type (Th)-2-inflammation in which the release of interleukin (IL)-4, IL-13, IL-5, and the immunoglobulin E (IgE) production increase eosinophilic survival." (PMID 36483465, 2022). "Among the different single nucleotide polymorphisms discovered in the IL-4 gene, rs2070874, located on the UTR region of the gene, has been shown to be associated with higher serum IgE levels and increased risk of asthma in different ethnic populations." (PMID 36292755, 2022). "Completed and ongoing clinical trials of therapeutic antibodies targeting IL-4/IL-13 axis and their receptors in AR and asthma patients." (PMID 35663523, 2022). "IL-4 and IL-13 can enhance bronchial remodeling and recruitment of mast cells, basophils, and eosinophils, aggravating airway inflammation in asthma." (PMID 36330226, 2022). "As noted, asthma is also a manifestation of excessive activation of Th2 cells, which leads to increased secretion of IL-4, IL-5, and IL-13 in asthmatic mice." (PMID 35682783, 2022). "There was also a reduction in the production of Th2 cytokines (IL-4 and IL-5), a key indicator of asthma-inducing immunology." (PMID 35455087, 2022). "In clinical trials, the levels of IL-12, IFN-γ, and Th1 percentage decreased in pneumonia and asthma children's peripheral blood, while the levels of IL-4 and IL-10 and the percentages MDSCs and Th17 increased." (PMID 36045657, 2022). "Further, many of the prominent underlying pathological features of CRSwNP, including high expression levels of type 2 cytokines (IL-4, IL-5, and IL-13, among others) and elevated IgE, are also key contributors to the pathology of asthma." (PMID 34536215, 2022).
asthma (continued). "The Th2-related cytokines such as IL-4 and IL-13 are of vital importance in the pathological process of asthma by inducing IgE production and airway mucus hypersecretion." (PMID 35281601, 2022). "Currently available biologics for severe asthma include the anti-IgE antibody, anti-IL-5 antibody, anti-IL-5 receptor antibody, and human anti-IL-4/13 receptor monoclonal antibody." (PMID 35454111, 2022). "STAT6 is activated by cytokines IL-4 and IL-13 and mediates the occurrence of allergic diseases, such as asthma, atopic dermatitis, and eosinophilic esophagitis." (PMID 35204186, 2022). "Pioglitazone demonstrated similar anti-inflammatory effects in a cockroach allergen-induced asthma model, suppressing airway hyperresponsiveness, serum IgE, and IL-4, IL-5, TNF-α, and TGF-β levels." (PMID 36230993, 2022). "In asthma patients, Th2 cells secrete more IL-4 to induce B cell activation, leading to excessive IgE secretion." (PMID 35682783, 2022). "We have yet to investigate the possible involvement of other immune cells known to produce IL‐4 in the context of asthma, such as basophils or activated ILC2s." (PMID 35758054, 2022). "Children with asthma also had a higher IL4/IFN-ɤ ratio, consistent with a predominant Th2 inflammatory state." (PMID 36140412, 2022). "During the inflammatory response, eosinophils also induce lymphocytes to synthesize and release cytokines such as IL-1β, IL-4, IL-6, and IL-13, which promote and exacerbate asthma attacks." (PMID 36408342, 2022). "Due to its key role in eosinophil development, release and recruitment to tissues, IL-5 has been identified as alongside IL-4 and IL-13 as key cytokines behind the pathophysiology of T2 asthma." (PMID 36232470, 2022). "Enrichment analysis of core targets showed that SYD exerted therapeutic effects on asthma mainly by regulating IL-4-mediated differentiation of Th0 cells." (PMID 36212941, 2022). "After cortisol hormone therapy, the levels of IL-4, IL-5, and IL-8 in the sputum of asthma patients were reduced, IL-13 expression was decreased in the bronchial epithelium in asthma patients." (PMID 35578178, 2022). "IL-4 and INF-γ levels in asthma patients have been associated with the T-bet/GATA-3 ratio, indicating an immune imbalance in asthma conditions." (PMID 36311189, 2022). "Discovered DMRs annotated to genes implicated in allergy and asthma, Th2 activation and eosinophilia (EPX, IL4, IL13, PRG2, CLC and ZFMP1) and genes previously associated with asthma and IgE in an EWAS of blood (ACOT7, SLC25A25)." (PMID 35344303, 2022). "In T2-high asthma, clinical symptoms result from inflammation driven by the cytokines interleukin-4 (IL4), IL5, and IL13, as well as alarmins [thymic stromal lymphopoietin (TSLP), IL25, IL33] and Immunoglobulin E (IgE)." (PMID 36237537, 2022). "The cytokines secreted by Th2 cells are mainly IL-4, IL-5, IL-13, and IL-9 which have different roles in the pathogenesis of asthma." (PMID 36032162, 2022). "To determine the relationship between PRB1 and type 2‐high asthma further, we detected the levels of IL‐2, IL‐4, IL‐5, IL‐6, IL‐10, IL‐13, IL‐17, and INF‐γ in the induced sputum supernatant." (PMID 35344278, 2022). "In asthma, airway inflammation caused by tumor necrosis factor (TNF)-α, IFN-γ, IL-4, and IL-13 dysregulate epithelial barrier activities." (PMID 35625578, 2022). "Pulmonary eosinophilia and high amounts of IL-4, IL-5, IL-13 and IgE in the lungs and serum are also characteristic of asthma." (PMID 36145419, 2022). "IL4 is an important cytokine involved in asthma development, and it has been reported that airway hyperresponsiveness, eosinophil infiltration, and inflammation are all symptoms of bronchial asthma that IL4 likely mediates." (PMID 36140412, 2022). "IL-4 and IL-13 have been studied for their involvement in the pathogenesis of allergic disorders such as asthma and atopic dermatitis through the activation of eosinophils and the production of immunoglobulin E (IgE) by B cells." (PMID 36235579, 2022).
asthma (continued). "Administration of anti-IL-6 antibodies during asthma induction increased IL-13, IL-4, and IL-5 protein levels in the BALF." (PMID 35408882, 2022). "The pathogenesis of asthma is mainly mediated by type-2 inflammation, with increased production of Th2 cytokines such as IL-4, IL-5, and IL-13 by Th2 cells and ILC2s." (PMID 35625578, 2022). "Th2-mediated inflammatory responses play critical roles in the pathogenesis of asthma by releasing cytokines such as IL-4 and IL-5." (PMID 35040955, 2022). "IL-4/IL-13 axis is important in the pathogenesis of AR and asthma in which the axis exerts a wide range of effects on inflammatory cells and structural changes to airway epithelial cells in AR and asthma." (PMID 35663523, 2022). "Among them, Th2 cells play a major role in asthma pathogenesis by secreting various cytokines such as IL-4, IL-5, IL-9, and IL-13, while IFN-γ secreted by Th1 inhibits Th2 function." (PMID 35815290, 2022). "Allergen-specific responses in asthma are attributed to a skew towards a Th2 phenotype, with elevated levels of serum interleukin-4 and IgE." (PMID 36317397, 2022). "IL-4 promotes IgE production by B lymphocytes and coats mast cells, leading to a rapid release of more proinflammatory mediators in asthma." (PMID 35745177, 2022). "The cytokines secreted by CD4+ T-cells, typically, type 2 cytokines such as IL-4, IL-5, and IL-13, are closely involved in asthma." (PMID 35745240, 2022). "Discovered DMRs and CpGs were annotated to genes reported to be associated with allergic asthma, Th2 activation, and eosinophilia (EPX, IL4, IL13), as well as to genes ACOT7 and SLC25A25 implicated in a blood EWAS of asthma and IgE." (PMID 35055381, 2022). "In particular, the pleiotropic roles of IL-4 and IL-13 in orchestrating Th2 responses in AR and asthma patients indicate that dual IL-4/IL-13 blockade is a promising therapeutic strategy for both diseases." (PMID 35663523, 2022). "The newest treatment options for severe uncontrolled asthma include the mAbs anti-IL-4/IL-13 dupilumab and the anti-thymic stromal lymphopoietin (TSLP) tezepelumab." (PMID 36140430, 2022). "Observational studies on type-2 cytokines in sputum also showed that mean IL-4, IL-5, and IL-13 mRNA expression and concentrations of these cytokines were increased in elderly patients with asthma." (PMID 36291665, 2022). "IL4 is an anti-inflammatory protein that can modulate inflammation, thus preventing asthma and vice versa." (PMID 36140412, 2022). "Aberrant T helper type 2 (Th2) inflammation is the most important pathological process for asthma, which is mediated by Th2 cytokines, such as interleukin (IL)-5, IL-4, and IL-13." (PMID 36078171, 2022). "IL-4 is characterized for its involvement in chronic inflammatory lung diseases such as asthma, and one study analyzed pulmonary angiogenesis under hypoxic conditions in an IL-4 knockout (KO) model." (PMID 35159396, 2022). "T helper cells are a key regulator during asthma pathogenesis; they regulate the secretion of many cytokines, including IL-13, IL-5 and IL-4 and involved in innate type 2 immunity." (PMID 36201519, 2022). "One study showed that TIPE2 levels in peripheral blood mononuclear cells (PBMCs) of asthma patients were lower than levels in healthy individuals and negatively correlated with eosinophil, IL-4, and IgE levels." (PMID 35572500, 2022). "In this study, sputum TIPE2 levels were significantly increased in patients with EA and positively correlated with sputum IL-4, IL-5, and IL-13 that promoted eosinophilic inflammation in asthma." (PMID 35572500, 2022). "Asthma is traditionally thought to result from inflammation driven by T2 high responses and mediated by cytokines including IL-4, IL-5, and IL-13, which are often produced after the recognition of allergens." (PMID 35330333, 2022). "If Th2-type cytokines IL-4 and IL-13 involvement in subepithelial fibrosis in asthma is acknowledged, pro-fibrotic effects of IL-17 are also well-documented." (PMID 35386663, 2022).
asthma (continued). "Conversely, STAT6 is a transcription factor present in Th2 cells with ability to induce secretion of IL-4, IL-5, and IL-13, which are responsible for the main features of asthma." (PMID 36685604, 2022). "TSLP is crucial for TH2 immunity, which is involved in asthma pathophysiology, as it induces the expression of TH2-associated inflammation drivers, such as IL-4 and IL-5." (PMID 35743783, 2022). "miR‐135b overexpression reduces IL‐4 levels, which is promising for alleviating airway inflammation in asthma." (PMID 36149748, 2022). "The concentration of IL-4 and IL-13 was significantly increased in the blood of pediatric asthma patients relative to the healthy control group." (PMID 36313877, 2022). "We found that at low levels of eosinophils, the secretion of cytokines such as L-12p70, IL-13, and IL-4 in patients with asthma increased, while in the ACO group, the opposite result was shown that most cytokines had a decreasing trend." (PMID 36311545, 2022). "It was further demonstrated that the cells exhibited elevated levels of IL-4/IL-13-induced genes, as well as asthma genes such as CSTI and POSTN, suggesting the involvement of these types of cells in mucus cell metaplasia." (PMID 36203653, 2022). "Secondly, patients with asthma have increased levels of plasma cytokines such as IL-4, IL-5, and IL-13 and chemokines such as monocyte chemoattractant protein-1 (MCP-1)." (PMID 35905078, 2022). "IL-4 immunoreactive mast cells have been detected in bioptic specimens of allergic rhinitis, asthma, and atopic dermatitis." (PMID 36430483, 2022). "Dupilumab, a monoclonal antibody (mAb) and a dual inhibitor of IL-4 and IL-13, has been approved for the treatment of atopic dermatitis and asthma." (PMID 36430483, 2022). "Differential methylation of IL‐4 and IL‐17 signaling pathways appeared to be affected by FeNO in asthma, as well as allergic asthma." (PMID 35344303, 2022). "Otherwise, asthma mice pretreated with Imuno TF presented reduced concentrations of IL-4 (5A), IL-5 (5B), and IL-13 (5C) in lung tissue compared to asthma mice." (PMID 36685604, 2022). "Mice exposed to A. niger develop airway hyperresponsiveness, the physiologic sine qua non of asthma, increased production of the type 2 cytokines IL-4, IL-5, and IL-13 in the lungs, along with an influx of eosinophils and elevated serum IgE levels." (PMID 35281012, 2022). "Previous data reported various cytokines, such as IL-4, IL-5, IL-13, and IL-33, increased in patients with asthma and AR in serum or lower respiratory tract specimens." (PMID 35348596, 2022). "The inflammatory process of asthma is mediated by helper T-2 cells and eosinophils in addition to the released cytokines, including interleukins (IL); IL-4, IL-5, and IL-13." (PMID 36263132, 2022). "Antagonising the IL-4 receptor α subunit (IL-4Rα) interferes with the downstream IL-4/IL-13 signalling, which is central to the pathogenesis of asthma." (PMID 36140430, 2022). "In certain severe asthma conditions, biologics such as omalizumab (anti‐IgE), mepolizumab, reslizumab and benralizumab (anti‐IL‐5 pathways), and dupilumab (anti‐IL‐4/IL‐13) represent major advances in asthma care." (PMID 40496383, 2022). "Of all the participants, one neonate in the HC group was diagnosed with both asthma and atopic dermatitis, and was surprisingly found to have the highest expression level of Il-4 in cord blood CD4+ T-cells." (PMID 35745240, 2022). "IL-4 and IL-13 contribute to asthma pathogenesis also by impairing the integrity of the airway epithelium." (PMID 35625801, 2022). "IL-4, as a central mediator of asthma, plays a pivotal role in the switching of the IgE isotype in B cells." (PMID 34991711, 2022). "The release of IL-25 from epithelial cells in asthma also leads to overproduction of IL-4, IL-5, IL-9, IL-13, and CCL11, which then initiate recruitment of eosinophils, DCs, ILC2s, basophils, T cells, and other immune cells." (PMID 36311787, 2022).
asthma (continued). "Among 10 hub genes, we strongly suggest IL6 and IL4 as prospective childhood asthma biomarkers since both of these biomarkers achieved a high systemic score in Cytohubba’s MCC algorithm." (PMID 36140412, 2022). "To distinguish the effects of LF in the population of T cells in OVA-induced asthma, we used Foxp3, IL-4, INF-γ, and CD4 antibodies to evaluate the differentiation of T cells." (PMID 36430662, 2022). "In support of this, type 2–high asthma is characterized by elevated levels of IgE and Th2 cytokines, including IL-4, IL-5, and IL-13." (PMID 34536215, 2022). "Many studies have shown that type 2 cytokines, including interleukin (IL)-4, IL-5, and IL-13, were related to allergic inflammation and these cytokines elevated in the sputum and the blood of patients with asthma and AR." (PMID 35348596, 2022). "IL-4 produced by Th2 cells played a central role in the development of asthma, in that it increased the expression level of inflammatory cytokines in the lung and ultimately stimulated the production of IgE." (PMID 35431951, 2022). "Subsequently, it was shown that IL-4-responsive B cells are important for Th2 polarization, and promoted clearance of helminthic infections, while worsening asthma and leishmaniasis." (PMID 35359977, 2022). "Epithelial cytokines known as alarmins resulted in the production of IL-4, IL-5, and IL-13, which play key roles in asthma pathogenesis." (PMID 36077310, 2022). "Previous research by other members of the research team found that QF alleviated asthma exacerbation by decreasing the levels of IL-4, IL-6, and IL-13 in the serum and inflammatory cells in the lung tissue of RSV-infected asthmatic mice." (PMID 36081945, 2022). "Previously, we successfully established an AD mouse model for the study of asthma and detected elevated levels of IL-4, IL-5, and IgE, confirming the involvement of Th2 inflammation in the progression from AD to asthma." (PMID 35177102, 2022). "Th2 cells secrete IL-4, IL-5, IL-9, IL-13 and other inflammatory factors, among which IL-4 and IL-13 are the regulators of asthma." (PMID 35744915, 2022). "IL-4 and IL-13, the cytokines upstream of STAT6, increased in human asthma, and clinical trials targeting the IL-4/IL-13/STAT6 pathway are ongoing." (PMID 35204186, 2022). "HES treatment in an ovalbumin (OVA)-induced asthma mouse model reduced IL-4, IL-5, IL-13, and IL-17 production, as well as OVA-specific IgE expression by inhibition of the GATA binding protein 3 (GATA3) transcription factor to the DNA." (PMID 35631330, 2022). "A humanized monoclonal IgG4 antibody called dupilumab binds to the alpha subunit of the interleukin-4 receptor (IL-4Rα) and inhibits the signaling of IL-4 and interleukin-13 (IL-13), which has been successfully applied for atopic dermatitis and asthma." (PMID 35222408, 2022). "Asthma is an allergic disease of immune imbalance, and overactivation of Th2 cells is induced in the lung to exacerbate the secretion of IL-4, IL-5, and IL-13 cytokines." (PMID 35682783, 2022). "In this study, the percentage of MDSCs, and the levels of IL-4 and IL-10 increased in asthma and pneumonia group, but the levels of IL-12 and IFN-γ reduced." (PMID 36045657, 2022). "Among these, IL6 and IL4 were screened out as highly potential biomarkers in childhood asthma since the gene also acquired a high systemic score in Cytohubba’s MCC algorithm." (PMID 36140412, 2022). "The level of IL-17 in the cell supernatant was significantly higher in the Th17-dominant asthma group than in the T2 asthma group, while that of IL-4 was significantly higher in cell supernatant of the T2 asthma group." (PMID 36303542, 2022). "The IL-4 gene is located on chromosome 5 in a region that has been reported to be correlated with asthma and other allergic disorders." (PMID 36292755, 2022).